DNMT1 (DNA methyltransferase 1)
Diseases named in the same sentence as DNMT1 in open-access papers (continued):
Sharing a sentence is not in itself a finding about the gene and the disease.
liver cancer (33 papers, 2012 to 2025). An epithelial or non-epithelial malignant neoplasm that arises from the liver. "The increased activity of DNMT1 causes the hepatocyte growth factors (HGFs) in liver cancer to be hypermethylated." (PMID 41011154, 2025). "DNMT1 has been identified as a serum biomarker event in cancer development, and DNMT1 has been also confirmed to be associated with HBV-related liver cancer." (PMID 36193503, 2022). "DNMT1 is important in maintaining cancer stem cells since upregulated miR-34a associated with DNMT1 inhibition can reduce the viability of liver cancer cells." (PMID 32308683, 2020). "Over-expression of DNMT1 correlates with increased genomic methylation and has been associated with miRNA dysregulation in liver cancer, in which DNMT1 over-expression is induced by IL-6 over-production." (PMID 25705251, 2014). "For instance, liver cancer upregulates the expression of DNMT3a and DNMT3b, while chronic hepatitis upregulates DNMT1 and DNMT3a." (PMID 41011154, 2025). "Next, we wanted to evaluate the survival probability of liver cancer patients with high-expression and low-expression of DNMT1, EHMT2, and UHRF1 genes." (PMID 38285887, 2024). "We here showed that LCSCs exhibited elevated DNMT1 activity and expression, lower miR-34a expression with higher promoter methylation, and stronger stemness, compared with the parental liver cancer cells." (PMID 32308683, 2020). "DNMT1 knockdown repressed DNMT1, increased miR-34a amounts by promoter demethylation, and reduced stemness in LCSCs, whereas DNMT1 overexpression had the opposite effects in liver cancer cells." (PMID 32308683, 2020). "This study demonstrated that miR-34a promoter methylation by abnormal DNMT1 activation resulted in miR-34a downregulation in LCSCs compared with the corresponding liver cancer cells." (PMID 32308683, 2020). "Remarkably, panobinostat, an epigenetic drug for treating different types of cancer, has shown inhibition of DNMT1 in liver cancer cell lines." (PMID 33375520, 2020). "The authors have demonstrated that epigenetic reprogramming induced by transient DNMT1 inhibition influences both malignant properties and the pool of hepatic cancer stem cells." (PMID 29228658, 2017). "Our results showed inhibition of DNA methylation by either 5-aza-dC treatment or knockdown of DNMT1 caused the induction of miR-31 expression, and consequently suppressed HDAC2 and CDK2 expression in liver cancer cells." (PMID 25797269, 2015). "Previous studies have observed DNMT1 overexpression in patients with lung and liver cancers who were smokers." (PMID 26317789, 2015). "LCSCs displayed increased DNMT1 activity and expression, reduced miR‐34a expression accompanied by enhanced promoter methylation, and heightened stemness properties compared to the original liver cancer cells." (PMID 40387409, 2025). "Thereby, inhibition of DNMT1/miR‐34a‐mediated FOXM1 overexpression could potentially suppress liver cancer by selectively targeting LCSCs." (PMID 40387409, 2025). "To explore the involvement of DNMT1 in the Sox9-mediated reduction in AY/AN-cHCC-CCA, we delivered a plasmid expressing full-length Dnmt1 into Sox9 CKO mice to investigate its association with SOX9 during liver cancer development." (PMID 39273023, 2024). "This confirmed that epigenetic silencing of miR-34a promotes stemness features in LCSCs, highlighting the DNMT1/miR-34a axis might represent a promising approach in treating human liver cancer by targeting LCSCs." (PMID 32308683, 2020). "The DNMT1 enzymatic inhibitory activity of panobinostat, a known pan inhibitor of histone deacetylases, agrees with experimental reports of its ability to reduce DNMT1 activity in liver cancer cell lines." (PMID 33375520, 2020). "Whether DNA methyltransferase 1 (DNMT1)/miR-34a/FoxM1 signaling promotes the stemness of liver cancer stem cells (LCSCs) remains unclear." (PMID 32308683, 2020).
liver cancer (continued). "This study aimed to assess whether methylation-based silencing of miR-34a by DNMT1 contributes to stemness features via FoxM1 upregulation in liver cancer cells." (PMID 32308683, 2020). "In conclusion, our in silico analysis revealed a high concomitant expression of the epigenetic genes DNMT1, EHMT2, and UHRF1 in liver cancer patients with inferior outcomes." (PMID 38285887, 2024). "Second, we only analyzed ZNF191/DNMT1/p‐AKT axis in hepatoma cells, thus our proposed signal pathway regulation requires further validation in mouse models of liver cancer and HCC patients." (PMID 35092191, 2022). "This novel DNMT1/miR-34a/FOXM1 signaling-mediated mechanism of stemness acquisition and maintenance in liver cancer offers a new potential therapeutic strategy for the treatment of human liver cancer." (PMID 32308683, 2020). "In liver cancer cells, TGF-β1 can regulate CD133 expression through the inhibition of DNMT1 and DNMT3b expressions; TGF-β1 stimulation results in a significant demethylation of CD133 promoter-1." (PMID 23560091, 2013). "The DNMT1-mediated methylation of BEX1 regulates stemness and tumorigenicity in liver cancer." (PMID 35795047, 2022). "Transfection with miR-34a mimic repressed the stemness of LCSCs, while miR-34a inhibitor significantly downregulated miR-34a and enhanced stemness, without affecting DNMT1 in liver cancer cells." (PMID 32308683, 2020). "The clinicopathological analysis demonstrated that high expression of DNMT1 protein was closely correlated with younger age (p = 0.017), high AFP level (p = 0.011), tumor venous invasion (p < 0.001), and a high BCLC (the Barcelona Clinic Liver Cancer staging) stage (p = 0.001) with the χ2 test." (PMID 35092191, 2022).
liver fibrosis (27 papers, 2015 to 2024). "DNMT1 is implicated in DNA methylation maintenance post-replication, with increased expression observed in liver fibrosis and a key role in driving the transformation of HSCs into myofibroblast-like cells." (PMID 39195573, 2024). "MALAT1 (Metastasis Associated Lung Adenocarcinoma Transcript 1) is another broadly recognized lincRNA, which is highly expressed in hepatic fibrosis tissues and interacts with DNMT1 both in human and mice." (PMID 39036601, 2024). "MiR-152 has been shown to downregulate DNMT1 expression, thereby reducing HSCs activation and ameliorating liver fibrosis by inhibiting PTCH1 methylation to enhance its expression and subsequently suppress the Hedgehog pathway." (PMID 39195573, 2024). "Sal B inhibits the epithelial–mesenchymal transformation of the hepatic stellate cells by regulating the miR-152/DNMT1 axis; thus, inhibiting liver fibrosis." (PMID 38405620, 2024). "The DNA methyltransferase 1 (DNMT1)-mediated epigenetic silencing of lncRNA H19 is associated with the activation of hepatic stellate cells, which is involved in liver fibrosis." (PMID 38540698, 2024). "Previously, we demonstrated that miR-152 promotes PTCH1 demethylation by inhibiting DNMT1, thereby controlling liver fibrosis." (PMID 37397418, 2023). "PTEN promoter hypermethylation/low expression or deletion has been observed in TGFβ-induced activated HSC-T6 cells in vitro as well as in a CCl4-induced mouse hepatic fibrosis model, which is mediated by DNMT1." (PMID 37056286, 2023). "Targeting PTEN alleviated liver fibrosis, while saponin A promoted the expression of PTEN by binding with DNMT1, thereby reducing liver fibrosis." (PMID 37505544, 2023). "Consistently, sennoside A can prevent liver fibrosis by binding DNMT1 and suppress DNMT1-mediated PTEN hypermethylation in HSC activation and proliferation." (PMID 33791228, 2021). "G9a expression was induced during liver fibrosis, and dual targeting of G9a and DNMT1 suppressed liver fibrogenesis in mice." (PMID 34069116, 2021). "In this regard, a previous study showed that DNMT1 mediates repression of Smad7 and subsequent hepatic stellate cell activation and liver fibrosis." (PMID 33456568, 2021). "DNMT1 expression is increased in activated HSCs and rat liver fibrosis tissue, which leads to enhanced methylation of the lncRNA H19 promoter and elevates H19 expression and ERK activation." (PMID 33791228, 2021). "The mechanism of action of H19 in liver fibrosis is related to DNA methylation, and the DNA methylation reader protein DNMT1 regulates the lncRNA H19/ERK (extracellular regulated protein kinases) signalling pathway in HSC activation and fibrosis." (PMID 32098245, 2020). "Studies in hepatic stellate cells and liver fibrosis models suggest that MiR-29 upregulates PTEN expression by targeting DNA methyltransferases such as Dnmt1, Dnmt3b, and Set1a to prevent excess liver fibrosis." (PMID 31703360, 2019). "Taken together, these data indicated that the downregulation of PTGIS in liver fibrosis was attributed to DNA methylation and PTGIS gene methylation was mainly caused by DNMT1 and DNMT3b." (PMID 29892223, 2018). "Taken together, these data indicated that downregulation of PTGIS in hepatic fibrosis was attributed to hypermethylation of PTGIS promoter which mainly induced by DNMT1 and DNMT3b." (PMID 29892223, 2018). "Our previous study showed that microRNA-152 (miR-152) inhibits liver fibrosis by attenuating DNA methyltransferase 1(DNMT1)-mediated PTCH1 methylation." (PMID 27588491, 2016). "Our results suggest that miR-152, which targets DNMT1, might have an effect on liver fibrosis after Rg1 treatment." (PMID 37397418, 2023).
liver fibrosis (continued). "DNMT1 and DNMT3B methylates the genes encoding regulator of calcineurin 1 (RCAN1), prostacyclin synthase (PTGIS), Septin9 and SAD1/UNC84 domain protein-2 (SUN2), promoting HSC activation and liver fibrosis." (PMID 34805276, 2021). "It is also possible that DNMT1 or TET3 regulates other lncRNAs in the process of hepatic fibrosis." (PMID 30534359, 2018). "In the case of liver fibrosis, which was investigated in a respective mouse model (fibrosis induced using carbon tetrachloride (CCl4)), DNMT1 was hypothesised to reduce Pten mRNA levels through hypermethylation of its promotor, indirectly influencing COLα1 (I) expression levels." (PMID 37373151, 2023). "Therefore, targeting PTEN or DNMT, via silencing the DNMT1 gene or using DNMT inhibitors to prevent PTEN hypermethylation and expression deficiency, and negatively regulate the AKT/ERK pathway, thereby inhibiting HSC activation and alleviating liver fibrosis." (PMID 37056286, 2023). "Therefore, the DNMT1-lncRNA H19 epigenetic pathway plays important roles in liver fibrosis." (PMID 32098245, 2020). "One example is the DNMT1-LncRNA H19 epigenetic pathway, which is involved in HSC activation and liver fibrosis." (PMID 34805276, 2021). "Suppression of Smad7 by DNA methyltransferase 1 promoted the phosphorylation of Smad2 and Smad3 that had been induced by HSC activation, or liver fibrosis in general." (PMID 25435153, 2015). "Collectively, miR-152 induced by Sal B, contributed to DNMT1 down-regulation and epigenetically regulated PTCH1, resulting in the inhibition of EMT in liver fibrosis." (PMID 26257392, 2015). "In liver fibrosis, RCAN1.4 was decreased by elevated methyltransferases DNMT1 and DNMT3b." (PMID 34707090, 2021).
Hyperglycemia (24 papers, 2013 to 2026). An increased concentration of glucose in the blood. "Although the data indicated that the hypermethylation in β cells from both humans and the cell line was due to hyperglycaemia, only in the cultured β cell line was the hyperglycaemia associated with significant increase in DNMT1 expression." (PMID 32653024, 2020). "We observed that three months of hyperglycaemia, in insulin-deficient Ins2Akita mice, decrease DNMT1 and DNMT3a expression levels." (PMID 30057682, 2018). "By contrast, three months of hyperglycaemia in insulin-deficient Ins2Akita mice resulted in the downregulation of DNMT1 and DNMT3a expression." (PMID 30057682, 2018). "Thus, methylation modification of DNMT1 may represent a potential mechanism of fetal programing by hyperglycemia causing abnormal kidney development through parental imprinting." (PMID 26258530, 2015). "Parallel to restoring DNMT1 expression, aPC reversed hyperglycemia-induced persistent hypomethylation of the p21 promoter." (PMID 36030260, 2022). "In retinal endothelial cells, hyperglycemia increases the binding of Dnmt1 and Tet2 to the promoter of the MMP-9 gene." (PMID 36397159, 2022). "We detected the DNMT1 protein level in CD31+ cells via immunofluorescent staining, and we found that H2S decreased the DNMT1 levels in vascular endothelial cells up-regulated by hyperglycemia." (PMID 36078059, 2022). "In agreement with above reports, our RNA-seq data showed that Dnmt1 was decreased and Dnmt3b was increased consistently in all three stem/progenitor cell-derived EVs subjected to hyperglycemia." (PMID 32942572, 2020). "Moreover, in retinal ECs, hyperglycemia and ROS production can induce the sustained overexpression of DNA (cytosine-5)-methyltransferase 1 (DNMT1), even after normalization of glucose levels, maintaining a pathological epigenetic memory." (PMID 38755006, 2024). "Together, these findings suggest that a suppressive intervention targeting DNMT1 is most likely to reduce the adverse toxicity to maintain normal glucose balance in the context of PI3K inhibition-induced hyperglycemia, further enhancing the effectiveness of anticancer treatments." (PMID 38755637, 2024). "Additionally, targeting DNMT1 potentially counteracts the pharmacological toxicity of hyperglycemia and insulin feedback stemming from PI3K inhibition." (PMID 38755637, 2024). "The effects of hyperglycemia on DNA methyltransferase 1, Tet methylcytosine dioxygenase 2 (TET2), 5-methylcytosine, 5-hydroxymethylcytosine, and the binding of TET2 and SP1 to the ROBO4 promoter, as well as the expression of ROBO4, zonula occludens 1 (ZO-1) and occludin were examined." (PMID 37430272, 2023). "To determine whether DNMT1 suppression is memorized in diabetic mice and whether aPC can reverse memorized DNMT1 suppression in vivo, we again reversed hyperglycemia in mice after 16 weeks for an additional 6 weeks (DM + SGLT2i)." (PMID 36030260, 2022). "In mice with persistent hyperglycemia for 22 weeks (DM-22), DNMT1 expression was reduced." (PMID 36030260, 2022). "While we did not reveal the dysregulation of DNMT expression using microarray data of short-term type 1 diabetes mouse models, three months of hyperglycaemia in insulin-deficient Ins2Akita mice resulted in the downregulation of DNMT1 and DNMT3a expression." (PMID 30057682, 2018). "Expression of DNMT1 was reduced in the aorta of diabetic (DM) animals and remained low despite normalization of blood glucose levels for 6 weeks after 16 weeks of persistent hyperglycaemia (DM-NG)." (PMID 30271984, 2018). "Interestingly, hyperglycaemia has previously been shown to increase the expression of a methyl transferase, Dnmt1, in clonal β cells." (PMID 23879380, 2013).
Hyperglycemia (continued). "To analyze whether aPC reverses tubular injury and senescence via DNMT1 in vivo, we reduced blood glucose levels in diabetic mice using SGLT2i starting at week 16 post induction of hyperglycemia for further six weeks (DM + SGLT2i), adding aPC in a subgroup of mice (DM + SGLT2i + aPC+PBS)." (PMID 36030260, 2022). "We found that hyperglycemia upregulated the transcript levels of ROBO4, DNMT1 and TET2, in an exposure time-dependent manner." (PMID 37430272, 2023). "Hyperglycemia conditions reduce MLH1 mitochondrial localization and hypermethylate its promoter with activated Dnmt1." (PMID 36397159, 2022). "Our data were in line with previous studies which demonstrated that hyperglycaemia significantly increased both DNMT activity and DNMT1 expression in retinal endothelial cells." (PMID 30057682, 2018). "Hyperglycemia also disrupts epigenetic regulation: overproduction of histone demethylases (e.g., JMJD3) and high DNMT1 levels suppress M2 polarization, while interventions such as DNMT1 inhibitors or modulation of MLL1-mediated H3K4me3 can restore M2 macrophage function." (PMID 41602470, 2026). "Interestingly, we found that LSK cells from GD adult offspring show a similar increase of DNMT1 protein, even as the models do not display overt hyperglycemia." (PMID 37988162, 2024). "However, changes in DNMT1 under hyperglycemia do not appear to impact its nucleocytoplasmic localization." (PMID 37470704, 2023). "ApoE−/− mice with hyperglycaemia (DM) for 16 weeks followed by 6 weeks of normoglycaemia (NG, achieved by SGLT2 inhibitor treatment) and concomitant aPC treatment were injected with a DNMT1 specific morpholinos (DM-NG-aPC-DNMT1-MO) or a non-specific control morpholino (DM-NG-aPC-Cont-MO)." (PMID 30271984, 2018).
esophageal squamous cell carcinoma (22 papers, 2015 to 2025). Esophageal squamous cell carcinoma (ESCC) is a type of esophageal carcinoma (EC) that can affect any part of the esophagus, but is usually located in the upper or middle third. "Our previous study showed DNMT1 is up-regulated in esophageal squamous cell carcinoma (ESCC), which is associated with methylation of tumor suppressors." (PMID 27286455, 2016). "In another example, lncRNA LUCAT1 was found to interact with DNMT1 but now to inhibit the ubiquitination in esophageal squamous cell carcinoma (ESCC)." (PMID 36533073, 2022). "For example, LUCAT1 can promote esophageal squamous cell carcinoma and clear cell renal cell carcinoma tumorigenesis by controlling the ubiquitination and stability of DNMT1 and the AKT/GSK-3β signaling pathway, respectively." (PMID 33097685, 2020). "LncRNA LUCAT1 affects the stability of DNMT1 and decreases the expression of tumor suppressor genes in a way of DNA methylation, thereby inducing tumorigenesis in esophageal squamous cell carcinoma." (PMID 31847842, 2019). "The objective is to detect methylation of the RASSF1A gene promoter and the expression of the DNA methyltransferase 1 (DNMT1) protein in esophageal cancer tissue and discuss their relationship with esophageal squamous cell carcinoma." (PMID 25886188, 2015). "The cheRNA LUCAT1 promotes the proliferation and metastasis of esophageal squamous cell carcinoma (ESCC) by increasing the stability of DNA methyltransferase 1 (DNMT1) and increases the methylation level of tumor suppressor factors, leading to the proliferation and metastasis of ESCC." (PMID 33937246, 2021). "Additionally, LUCAT1 promotes tumorigenesis by controlling ubiquitination and stability of DNA methyltransferase 1 in esophageal squamous cell carcinoma." (PMID 31399501, 2019). "Studies have shown that silencing DNMT1 inhibits the proliferation, metastasis, and invasion of esophageal squamous cell carcinoma (ESCC) cells." (PMID 41462671, 2025). "It is worth noting that after high-level expression of miR-126, it can inhibit DNMT1, thereby affecting the expression level of ADAM9 through the pathway, and then regulating the related physiological functions of esophageal squamous cell carcinoma." (PMID 32875951, 2020). "Aberrantly upregulated DNMT1 and the downregulation of miR-126 associated with promoter hypermethylation of its host gene EGFL7 were observed in esophageal squamous cell carcinoma (ESCC)." (PMID 31850200, 2019). "In esophageal squamous cell carcinoma, a distinct model was proposed, in which, the lncRNA LUCAT1 binds DNMT1 to protect it from ubiquitination, while LUCAT1 knock-down promotes ubiquitination of DNMT1 through UHRF1 (Ubiquitin-Like PHD and RING Finger Domain-Containing Protein 1)." (PMID 35292092, 2022). "Earlier studies also showed that silencing DNMT1 could upregulate RASSF1A expression and suppress RASSF1A methylation in esophageal squamous cell carcinoma." (PMID 30615685, 2019). "However, the function of DNMT1 in CSCs of esophageal squamous cell carcinoma (ESCC) remains unclear." (PMID 29721170, 2018).